SNX1 (sorting nexin 1)
Diseases named in the same sentence as SNX1 in open-access papers (continued):
Sharing a sentence is not in itself a finding about the gene and the disease.
tumor (12 papers, 2014 to 2026). "Noticeably, the reduction of SNX1 protein in GC tissues was significantly associated with bigger tumor size (p = 0.0294), poor nodal status (p = 0.0286), and poor tumor p-stage (p = 0.0285)." (PMID 29868263, 2018). "SNX1 is a putative tumor suppressor gene, and the encoded protein is a member of a large family of endocytic proteins that help determine the fate of internalized receptors as the receptors reach the early endosome." (PMID 24700353, 2014). "Given its known regulatory functions and tumor-suppressive potential, investigating the expression pattern, functional significance, and underlying mechanisms of SNX1 in OV may uncover new insights into disease pathogenesis and offer opportunities for therapeutic intervention." (PMID 41487280, 2026). "The consistent enrichment of these pathways supports a putative regulatory role for SNX1 and provides a basis for further investigation into its mechanistic involvement in tumor progression." (PMID 41487280, 2026). "Collectively, our findings identify SNX1 as a tumor suppressor and potential therapeutic target in OV, functioning through regulation of cell cycle, apoptosis and migration." (PMID 41487280, 2026). "In this study, we identified SNX1 as a potential tumor suppressor in OV, exhibiting a multifaceted role in the regulation of cell proliferation, epithelial–mesenchymal transition and drug sensitivity." (PMID 41487280, 2026). "Drug sensitivity analysis demonstrated a synergistic anti-tumor effect between SNX1 overexpression and paclitaxel treatment." (PMID 41487280, 2026). "Analysis of the TCGA (421 tumor samples) and GTEx (88 normal samples) datasets showed that SNX1 expression was significantly lower in OV tissues relative to normal ovarian tissues (P < 0.05)." (PMID 41487280, 2026). "In this study, we have discovered that a cell penetrating peptide designed to mimic the EGFR binding domain of SNX1 can induce tumor regression in vivo." (PMID 36253541, 2023). "The interactions of EGFR with MUC1 and SNX1 have both been targeted and shown efficacy in animal mouse tumor models." (PMID 37720348, 2023). "We found that 83.33% (55/60) of the tumor tissues showed immunohistochemical evidence of significant SNX1 reduction." (PMID 29868263, 2018). "Taken together, we propose here that SNX1 serves as a tumor suppressor and prognostic marker that reduces tumor cell malignancy for GC." (PMID 29868263, 2018). "Small interfering RNA knockdown of SNX1 levels in tumor cell lines resulted in increased proliferation, decreased apoptosis, decreased anoikis, increased EGFR phosphorylation after EGF stimulation, and increased downstream signaling." (PMID 24700353, 2014). "As a potential tumor suppressor, SNX1 is crucial in the development and progression of cancers." (PMID 40421300, 2025). "A study on 90 patients with detailed follow-up information showed that tumors with higher SNX1 protein level were correlated with better clinicopathologic stages (p = 0.0285), nodal status (p = 0.0286), smaller tumor sizes (p = 0.0294) and a better survival rate in patients with GC (p = 0.0245)." (PMID 29868263, 2018). "Ectopic SNX1 expression also prevented cell growth and increased drug sensitivity of tumor cells." (PMID 29954076, 2018). "Based on these previous investigations and our present study, we hypothesize that SNX1 may act as an inhibitor of cell proliferation in many tumor cells." (PMID 29868263, 2018). "Despite these findings, the expression of SNX1 in other tumor tissues and the role of SNX1 in the development and metastasis of other tumor tissues remains unknown and its detailed clinical value remains to be elucidated." (PMID 29868263, 2018). "There is an emerging link being established between the retromer complex and Notch signalling in other developmental contexts and the slight tumour suppression that we see in snx-1 mutants could be due to the retromer complex directly affecting the trafficking of the Notch receptor." (PMID 34555015, 2021).
tumor (continued). "As a result, they observed an upregulation of the tumor suppressor marker E-cadherin, and downregulation of the EMT marker Vimentin, whereas the effects were reversed upon reducing the levels of SNX1." (PMID 36612066, 2022). "Although no study revealed the roles of SNX21 in cancer, its family genes, such as SNX1, SNX5 and SNX9 were suggested to be tumor suppressor related." (PMID 31565549, 2019). "A large number of genes that function as tumour and growth suppressors, such as PHACTR4 and ARID4A, as well as genes that correspond to chemotherapy/radiotherapy response genes, such as SNAI1 and SNX1, were overexpressed." (PMID 32543350, 2020).
cancer (10 papers, 2017 to 2026). A tumor composed of atypical neoplastic, often pleomorphic cells that invade other tissues. "Here, we have utilized the BAR domain of Sorting Nexin 1 to create a peptide-based therapeutic (cSNX1.3) that promotes cell death in EGFR-expressing cancer." (PMID 36253541, 2023). "In a study of 150 cases of GC, including 60 cases with paired paracancerous and cancer tissues and 90 cases with detailed follow-up information, SNX1 expression was analyzed by immunohistochemistry." (PMID 29868263, 2018). "Our study on paired paracancerous and cancer tissues showed that SNX1 protein expression remarkably decreased in GC tissues (50/60, 83.33%)." (PMID 29868263, 2018). "However, it is also possible that SNX1 overexpression perturbs endocytic sorting contributes to cancer progression." (PMID 29954076, 2018). "Beyond SNX1, other sorting nexin (SNX) family members significantly influence cancer progression and therapy response through diverse mechanisms." (PMID 41487280, 2026). "That same group and others also observed a significant decrease of SNX1 protein in human CRC tumors, reinforcing the close link between SNXs and cancer." (PMID 28179995, 2017). "Moreover, phosphorylation at corresponding sites in SNX1, SNX3, SNX12, and SNX17 has been reported in various cancer types, hinting at a potential link between SNX phosphorylation and disease states." (PMID 40349777, 2025).
infection (7 papers, 2014 to 2024). The state of being infected such as from the introduction of a foreign agent such as serum, vaccine, antigenic substance or organism. "In this context, it is interesting to note that Salmonella enterica serovar Typhimurium acquire SNX1 and SNX3, and SNX1 is found on spacious vacuole-associated tubules early in the infection process." (PMID 26042774, 2015). "Remarkably, infection decreased the co-immunoprecipitation of CI-MPR with FLAG-SNX5 with minimal effects on the co-immunoprecipitation of SNX1 with FLAG-SNX5." (PMID 28252385, 2017). "Thus, we first used confocal imaging to investigate the distribution of SNX27, Vps35 and SNX1 in the early phase of infection." (PMID 39359939, 2024). "To distinguish whether the observed effects of SNX27 depletion are associated with its contribution to the SNX27:Retromer:ESCPE-1 complexes, we examined the effect of Vps35 and SNX1 + 2 depletion on the expression of pM74 in the L phase of infection." (PMID 39359939, 2024). "Therefore, additional targets apart from Rab1 and Snx1 during infection of macrophages or protozoan hosts could exist." (PMID 35204756, 2022). "To test if Snx1 and Snx2b proteins are needed to protect the viral RNA in plants, we knocked down Snx1 and Snx2b levels via VIGS and used CNV20Kstop missing the p20 silencing suppressor to allow for efficient RNAi activity during infection." (PMID 33370420, 2020). "As we have previously reported, IncE co-immunoprecipitates with FLAG-SNX5 in infected cells, and infection does not appreciably diminish steady-state levels of SNX1, VPS35, or CI-MPR." (PMID 28252385, 2017). "The role of Snx1 and its modification for infection is not clarified in detail." (PMID 35204756, 2022). "Other members of the SNX–BAR–retromer complex, SNX1 and SNX2, are not recruited to Lm entry sites, suggesting a possible differential recruitment and role of SNX–BAR proteins during infection." (PMID 29666193, 2018). "The importance of SNX1, VCL and PAK1 for infection of HeLa cells with MHV could not be confirmed (grey)." (PMID 25375324, 2014).
nervous system disease (1 paper, 2020). "For instance, in OPC protein–protein interaction (PPI) network, proteins involved in Golgi vesicle transport (such as Vamp3, Golga7, Vti1b and Snx1), Cell redox homeostasis (such as Tnx2 and Gsr), nervous system disease (such as Got1, Gm2a, Apoe and Cst3) and other functions were identified." (PMID 32974003, 2020).
SNX1 also shares sentences with these, for which no sentence is quoted: amyloid (1 paper); aortic aneurysm (1); breast carcinoma (1); chlamydial infection (1); clear-cell renal-cell carcinoma (1); diabetes (1); gastrointestinal carcinoma (1); leukemia (1); neurodegenerative disease (1); Parkinson disease (1).